NR5A1 (nuclear receptor subfamily 5 group A member 1)
Diseases named in the same sentence as NR5A1 in open-access papers (continued):
Sharing a sentence is not in itself a finding about the gene and the disease.
hypospadias (21 papers, 2011 to 2025). Hypospadias is the displacement of the urethral meatus on the ventrum of the penis. "In this study, we utilized WES to identify previously unreported NR5A1 variants in 4 unrelated patients presenting with varying degrees of hypospadias, ambiguous genitalia, and gonadal dysgenesis." (PMID 41398764, 2025). "NR5A1 mutations were reported in individuals with hypospadias, micropenis, and cryptorchidism, all clinical features that align closely with the TDS phenotype." (PMID 41595460, 2025). "A large-scale whole-exome sequencing (WES) study revealed that approximately 27% of severe hypospadias cases carried rare damaging variants in genes critical to testosterone synthesis and signaling, including AR, NR5A1, and SRD5A2." (PMID 41595460, 2025). "NR5A1 mutations are associated with a large spectrum of disorders of sex development (DSDs), including isolated cryptorchidism, male infertility, and hypospadias." (PMID 41595460, 2025). "Gene mutations in androgen receptor (AR), 5-α reductase (SRD5A2), and steroidogenic factor 1 (NR5A1) are linked to hypospadias formation." (PMID 39642224, 2024). "In this study, our patient is a 13 months’ old child with short penis and hypospadias, which are different from most children with NR5A1 variants as a labial mass and clitoral hypertrophy." (PMID 34112222, 2021). "Normal testosterone concentrations, at least in early childhood, have been found in NR5A1 variant patients with cryptorchidism, hypospadias and micropenis, as well as in 46,XY subjects presenting with a female phenotype." (PMID 33202802, 2020). "This NR5A1 mutation was previously reported in association with mild hypospadias, and a possible digenic inheritance was proposed to explain the phenotypic heterogeneity." (PMID 28033660, 2016). "In the 33 cases of 46,XY DSD with hypospadias only, we identified a single NR5A1 mutation (3%)." (PMID 22028768, 2011). "Similarly, NR5A1 sequence variants have been described in males with isolated hypospadias." (PMID 33202802, 2020). "Our findings not only expand the known mutational landscape of NR5A1 but also emphasize its critical role in DSD and hypospadias." (PMID 41398764, 2025). "The identification of 4 novel NR5A1 variants in our cohort of patients with DSD and hypospadias provides critical insights into the molecular etiology and phenotypic spectrum of this clinically heterogeneous condition." (PMID 41398764, 2025). "NR5A1 should be included in first-tier genetic testing for children with unexplained hypospadias or DSD, especially when accompanied by biochemical evidence of primary gonadal failure." (PMID 41398764, 2025). "This discovery highlights the indispensable role of Nr5a1+ extragenital cells in urethra closure, shedding light on the biology of penis formation and potential implications for human hypospadias." (PMID 39642224, 2024). "Variants in NR5A1 are associated with different reproductive phenotypes in humans, such as disorders of sex development (DSD), hypospadias, and POI." (PMID 36793102, 2023). "Family history of one of our index patients revealed premature menopause, menstrual disorders and isolated hypospadias in three relatives harboring the same p.Arg84Cys NR5A1 variation." (PMID 33202802, 2020). "This situation is especially apparent for changes in steroidogenic factor-1 (SF-1; encoded by NR5A1), where clinical and endocrine features ranging from complete gonadal dysgenesis through to hypospadias or male factor infertility can be seen." (PMID 31745530, 2019). "For instance, the spectrum of NR5A1 mutations presented in our 46,XY cohort as CGD (two patients), PGD (four patients), hypospadias (one patient) and DASA (one patient); additionally, it has also been shown to include spermatogenic failure." (PMID 27899157, 2016).
hypospadias (continued). "Mutations of the NR5A1 gene encoding steroidogenic factor-1 have been reported in association with a wide spectrum of 46,XY DSD (Disorder of Sex Development) phenotypes including severe forms of hypospadias." (PMID 22028768, 2011). "We evaluated the frequency of NR5A1 gene mutations in a large series of patients presenting with 46,XY DSD and hypospadias." (PMID 22028768, 2011). "This argues strongly for the inclusion of NR5A1 in 1st-tier genetic testing panels for any child presenting with unexplained hypospadias, ambiguous genitalia, or gonadal dysgenesis, especially when accompanied by biochemical evidence of hypergonadotropic hypogonadism." (PMID 41398764, 2025). "Ablation of Nr5a1+ cells leads to severe hypospadias and alters cell differentiation in the penis." (PMID 39642224, 2024). "In about 20–30% of 46,XY DSD cases, NR5A1 variants are inherited from non-affected or later affected mothers and less frequently non-mosaic asymptomatic and sometimes symptomatic (hypospadias) fathers transmit the NR5A1 variant to their children." (PMID 37185284, 2023). "While our 46,XY cases with NR5A1 variations in the LBD presented with a predominant female phenotype, others have reported cases with variants in same and similar location with a rather male typical phenotype, e.g., hypospadias and anorchia." (PMID 33202802, 2020). "Mutations in NR5A1 were observed in 5/77 (6.5%) cases of 46,XY DSD including hypospadias." (PMID 22028768, 2011). "Notably, the phenotypic manifestations extended from isolated hypospadias in a 46,XY male (Case 1) to severe genital ambiguity (Case 4) and, remarkably, to virilized genitalia in a 46,XX infant (Case 3), illustrating NR5A1’s capacity to override chromosomal sex." (PMID 41398764, 2025). "In a large study on hypospadias, it was concluded that heterozygous loss-of-function mutations in NR5A1 could be found in severe forms of hypospadias, but not found frequently in association with minor forms of hypospadias." (PMID 22028768, 2011). "This technology recently revealed that an NR5A1 intronic structural variant found in a large family with individuals presenting variable 46, XY DSD phenotypes, such as hypospadias, reduced fertility, and dysgenic testes, caused due to nonsense‐mediated decay." (PMID 39081229, 2025).
male infertility (19 papers, 2011 to 2025). The inability of the male to effect fertilization of an ovum after a specified period of unprotected intercourse. "Our primary objective was to identify rare NR5A1 variants and generate preliminary evidence to guide future research on the genetic basis of male infertility in West Africa." (PMID 41386844, 2025). "NR5A1 has only been associated with three alerts, all related to genetic variants linked to disorders of sex development, male infertility, and primary ovarian failure." (PMID 39065726, 2024). "Other pathogenic variants were identified in NR5A1 gene that is notoriously involved in male infertility." (PMID 33076341, 2020). "This is consistent with our recent findings that mutations in NR5A1 can lead to severe spermatogenic failure in 4% of otherwise unexplained cases of male infertility." (PMID 22028768, 2011). "Mutations of NR5A1 were also found to be involved in male infertility." (PMID 41595460, 2025). "Our study highlights the relevance of NR5A1 in male infertility screening and emphasizes the importance of incorporating African populations into reproductive genetics research." (PMID 41386844, 2025). "With this CYP17A1 cKO model they showed that NR5A1 depletion in Leydig cells of mature male mice can result in male infertility, whilst depletion of NR5A1 in theca cells of mature female mice mainly caused impaired steroidogenesis, with fertility being preserved." (PMID 37726790, 2023). "However, up to now, for only three genes, i.e., NR5A1, DMRT1, and TEX11, associations with male infertility have been evidenced in independent biological and functional studies." (PMID 31963602, 2020). "Loss-of-function changes in NR5A1 in 46,XY individuals are associated with a spectrum of phenotypes in humans ranging from a lack of testis formation to male infertility." (PMID 27378692, 2016). "Male infertility has been also related to the presence of NR5A1 defects." (PMID 28033660, 2016). "NR5A1, encoding for Steroidogenic Factor 1 (SF-1), is probably one of the most complex genes studied in DSDs, associated with a wide spectrum of DSD cases ranging from XY gonadal dysgenesis to male infertility, as well as primary ovarian insufficiency in women." (PMID 36158204, 2022). "Moreover, the absence of NR5A1 variants in four patients despite similar phenotypes emphasizes the genetic heterogeneity of male infertility and the potential contribution of additional genes or environmental factors, reinforcing the value of broader genetic studies in underrepresented populations." (PMID 41386844, 2025). "Many genes have been investigated in the context of male infertility; monogenic variants are correlated with disruptive spermatogenesis, resulting in reduced sperm counts and male infertility, for instance PRM1, NR5A1, MTHFR, and MTSR." (PMID 38540436, 2024).
disorders of sex development (16 papers, 2008 to 2025). "NR5A1/SF-1 variants are associated with a broad spectrum of phenotypes across individuals with disorders of sex development (DSDs)." (PMID 39337600, 2024). "Although pathogenic variants in NR5A1 are known to cause a spectrum of disorders of sex development (DSD), individuals with 46,XY DSD with fully female internal and external genitalia are relatively rare." (PMID 39149602, 2024). "Recently, we encountered a patient with 46,XY disorder of sex development (DSD) with a novel missense variant p.R350W in the ligand-binding domain (LBD) of NR5A1." (PMID 36743925, 2022). "Due to its critical role in gonadal development and testicular differentiation, loss-of-function mutations in NR5A1 cause 46,XY disorders of sex development (DSD)." (PMID 36743925, 2022). "Mutations in the nuclear receptor subfamily 5 group A member 1 (NR5A1) are the underlying cause of 10-20% of 46,XY disorders of sex development (DSDs)." (PMID 35865014, 2022). "Variants of NR5A1 are often found in individuals with 46,XY disorders of sex development (DSD) and manifest with a very broad spectrum of clinical characteristics and variable sex hormone levels." (PMID 33202802, 2020). "Mutations in NR5A1 are emerging as a frequent genetic cause of human 46,XY disorders of sex development (DSD), having been identified throughout the globe." (PMID 28033660, 2016). "NR5A1 loss-of-function mutations are increasingly found to be the cause of 46,XY disorders of sex development (DSD)." (PMID 22909003, 2013). "We have analyzed the gene encoding SF1 (NR5A1) in a cohort of 27 patients with 46,XY disorders of sex development (DSD) from the German network of DSD." (PMID 17694559, 2008). "The 107 cases included 14 with Klinefelter syndrome (KS) (13%), 1 with mosaic KS, 4 with sex development disorders (2 testicular XX, 1 NR5A1 gene mutation, and 1 mild androgen insensitivity syndrome) (4%), 9 with other non-obstructive azoospermia etiologies (8%), and 79 with undefined causes." (PMID 36449967, 2022). "In 46,XY individuals, NR5A1‐related phenotypes may range from disorders of sex development (DSD) to oligo/azoospermia, and in 46,XX individuals, from 46,XX ovotesticular and testicular DSD to primary ovarian insufficiency (POI)." (PMID 28033660, 2016).
endometriosis (16 papers, 2012 to 2026). The growth of functional endometrial tissue in anatomic sites outside the uterine body. "On the other hand, the NR5A1 promoter region was enriched with acetylated H3 and H4 in endometriosis versus disease-free tissues, correlating with its reported overexpression in endometriosis." (PMID 40590223, 2025). "The more important experiment will be to address the methylation status and expression of GATA6 and NR5A1 in the eutopic endometrium of women with endometriosis." (PMID 24603652, 2014). "The great majority of stromal cells in endometriotic peritoneal implants, deep-infiltrating endometriosis, or ovarian endometriomas contain similar aberrant levels of mRNA/protein, most notably NR5A1, GATA6, and aromatase, in part due to DNA methylation differences, which control gene expression." (PMID 40590223, 2025). "Epigenetic silencing of SF1 is lost in endometriosis due to hypomethylation of NR5A1." (PMID 40792071, 2025). "In addition, steroidogenic factor-1 (SF-1; encoded by NR5A1) and aromatase (encoded by CYP19A1) are also overexpressed in the ESCs of patients with endometriosis." (PMID 34531822, 2021). "One remarkable finding from this analysis was that it correctly identified the HOXA cluster, NR5A1, and PGR—genes that are aberrantly methylated and differentially expressed in endometriosis—as highly significant." (PMID 24603652, 2014).
premature ovarian failure (12 papers, 2011 to 2025). "Mutations of NR5A1 lead to many disorders and phenotypes, including premature ovarian failure, adrenocortical insufficiency, sex reversal, and spermatogenesis failure." (PMID 32093223, 2020). "In this group, five mothers had the same mutation, and 2 of them had premature ovarian failure, indicating that 46, XX individuals with NR5A1 mutations can have a natural pregnancy." (PMID 30425642, 2018). "Molecular and phenotypic features of 46,XX sporadic premature ovarian failure (POF) cases with NR5A1 mutations." (PMID 24073220, 2013). "Human variants in CITED2, such as in NR5A1, are associated with premature ovarian failure (POF)." (PMID 36013096, 2022). "Furthermore, NR5A1 mutations were found in 46,XX patients with premature ovarian failure and primary ovarian insufficiency." (PMID 28459839, 2017). "In addition to causing 46,XY DSD, NR5A1 mutations are a known cause of premature ovarian failure (POF)." (PMID 25497574, 2014). "Molecular and phenotypic features of premature ovarian failure (POF) cases in 46,XY DSD families with NR5A1 mutations." (PMID 24073220, 2013). "As mutations involving the NR5A1 gene have been associated disorders of sexual development (DSD) including anorchia, and primary ovarian insufficiency, we analysed the complete coding sequence of this gene." (PMID 21853106, 2011). "NR5A1 mutations are linked to a broad range of gonadal development disorders, spanning from DSD to oligo/azoospermia in 46XY individuals and 46XX ovotesticular and testicular phenotypes to primary ovarian failure in 46XX individuals." (PMID 40247401, 2025). "NR5A1 mutations are associated with a wide spectrum of disorders of gonadal development, ranging from DSD to oligo/azoospermia in 46,XY individuals and 46,XX ovotesticular and testicular phenotypes to primary ovarian failure in 46,XX individuals." (PMID 28033660, 2016). "Although mutations in NR5A1 have been reported in a small proportion of women with primary ovarian insufficiency (POI), NR5A1 mutations were not identified in 70 patients with POI in our cohort." (PMID 28033660, 2016).
adenoma (10 papers, 2013 to 2024). A neoplasm arising from the epithelium. "CDK9 and CDK18 were upregulated in NR5A1-adenomas, whereas CDK4 and CDK7 were upregulated in POUF1-adenomas." (PMID 35260162, 2022). "In contrast, the expression of the different genes encoding cyclins, CDK and CDK inhibitors among NR5A1-, POU1F1- and TBX19-adenomas showed only subtle differences." (PMID 35260162, 2022). "While 81.8% of the POU1F1-derived functioning adenomas were found to be recurrent upon follow up, that was the case for only 50% of the NR5A1-derived NFPA." (PMID 33261069, 2020). "Thus, NR5A1-, POU1F1- and TBX19-derived adenomas shared the same expression level of most genes encoding the different cyclins, CDK and CDK inhibitors." (PMID 35260162, 2022). "By contrast, the expression of genes that encode cyclins and CDK and CDK inhibitors among TBX19, NR5A1, and POU1F1 adenomas is not so different." (PMID 36968144, 2023). "Several of the genes encoding kinase presented isoforms, resulting from alternative splicing of mRNA: kinases PAK7 and STK26 in NR5A1-derived tumors, kinase PPIP5K2 in POU1F-derived adenomas and kinases like PPIP5K2 and kinases WEE1 and STK17 in the TBX19 tumors." (PMID 35260162, 2022).
Azoospermia (10 papers, 2016 to 2025). Absence of any measurable level of sperm,whereby spermatozoa cannot be observed even after centrifugation of the semen pellet. "Patients with NR5A1 gene variants presented with serious conditions, including micropenis, cryptorchidism, azoospermia, and radiological abnormalities of the spleen." (PMID 39623453, 2024). "p.Gly91Ser was the first NR5A1 variant to be reported in two siblings, a man with azoospermia and his sister with POI." (PMID 38737775, 2023). "Pathogenic variants of NR5A1 are responsible for a wide spectrum of phenotypes with autosomal dominant inheritance including disorders of sex development and oligospermia-azoospermia in 46,XY adults." (PMID 37409232, 2023). "NR5A1 mutations are associated with a wide spectrum of gonadal development disorders, ranging from DSDs to oligo/azoospermia in 46, XY individuals." (PMID 30425642, 2018). "In two patients, a causal variant was found that could explain their azoospermia (heterozygous variant in NR5A1 and hemizygous variant in RBBP7)." (PMID 39180390, 2025). "Therefore, we performed a comprehensive NR5A1 sequence analysis in almost 500 well-characterised and predominantly Caucasian patients with azoospermia or severe oligozoospermia." (PMID 29527098, 2018). "In 46, XY males harboring NR5A1 mutations, the presentation ranged from complete gonadal dysgenesis (CGD), partial gonadal dysgenesis (PGD) with micropenis, hypospadias and/or cryptorchid, to azoospermia without abnormal external genitalia development." (PMID 39623453, 2024).
cryptorchidism (10 papers, 2014 to 2025). The failure of one or both testes of a male fetus to descend from the abdomen into the scrotum during the late part of pregnancy. "Mutation analysis of INSL3/RXFP2 genes has been suggested in patients with a history of cryptorchidism, and mutations in the NR5A1 gene are emerging as a significant cause of primary spermatogenic impairment associated or not with cryptorchidism." (PMID 32486230, 2020). "A novel de novo heterozygous variant of the NR5A1 gene was identified in a boy with 46,XY DSD presenting with penoscrotal transposition, hypospadias, and cryptorchidism." (PMID 40723147, 2025). "The NR5A1/SF-1 c.437G>C/p.Gly146Ala variant is common in individuals with a DSD and has been suggested to act as a susceptibility factor for adrenal disease or cryptorchidism." (PMID 37432935, 2023). "Knockout experiments in mice clearly show independent requirements for INSL3/RXFP2 and androgens in testicular descent; nevertheless causative mutations in INSL3, RXFP2, AR (androgen receptor) or the Leydig cell regulator NR5A1 (steroidogenic factor-1), are rare in cases of cryptorchidism." (PMID 30083133, 2018).
gonadal dysgenesis (10 papers, 2016 to 2025). A congenital disorder characterized by the presence of extremely hypoplastic gonads preventing the development of secondary sex characteristics. "Mutations in NR0B1 cause X-linked adrenal hypoplasia congenita, with associated HH, whereas mutations in NR5A1 are associated with 46,XY sex reversal or gonadal dysgenesis, and 46,XX is associated with premature ovarian insufficiency." (PMID 31220230, 2019). "Over the following two decades, additional studies expanded the clinical spectrum of NR5A1 variants, showing that most affected patients have preserved adrenal function but widely variable degrees of gonadal dysgenesis, ranging from complete testicular failure to mild undervirilization." (PMID 41303802, 2025). "Mutations in NR5A1, DMRT1, and MAP3K1 are other leading causes, but together with mutations in the SRY gene, they explain less than 40% of all non‐syndromic forms of 46 XY gonadal dysgenesis." (PMID 40747867, 2025).